LEP (leptin)
Diseases named in the same sentence as LEP in open-access papers (continued):
Sharing a sentence is not in itself a finding about the gene and the disease.
Obesity (continued). "Obesity and metabolic syndrome are recognized by decreased serum adiponectin in parallel with intensified circulating leptin concentrations." (PMID 40282897, 2025). "At the same time, resistance to leptin during obesity impairs the regulation of hunger and energy use, further contributing to fat accumulation." (PMID 40016558, 2025). "In this review, we highlight the therapeutic potential of combining molecules targeting GPCR signaling with leptin for obesity treatment." (PMID 41016636, 2025). "Obesity-related GERD patients commonly exhibit elevated leptin levels and leptin receptor (ObR) downregulation, a state of leptin resistance." (PMID 41384250, 2025). "The knowledge about the participation of genes like Fat mass and obesity-associated (FTO) and Transmembrane protein (TMEM) 18 and adipokines like leptin and adiponectin, in asthma, under the influence of obesity, is still scarce." (PMID 39159917, 2025). "As it was discovered 30 years ago, our understanding of leptin and its role in the pathophysiology of obesity has advanced significantly." (PMID 41016636, 2025). "On the other hand, obesity is characterized by excessive lipid accumulation and elevated circulating leptin levels, both of which contribute to insulin resistance and compensatory hyperinsulinemia, leading to systemic inflammation and oxidative stress." (PMID 40723795, 2025). "Prior publicationshave reported significant associations between the LEP gene2548G>A polymorphism and key risk factors for MASLD including obesity,dyslipidemia, diabetes, IR, and hypertension." (PMID 41165450, 2025). "Both central and peripheral ER stress contribute to leptin resistance, which promotes energy imbalance, obesity, and NAFLD." (PMID 41492457, 2025). "Leptin, calprotectin, and adiponectin levels are influenced by various systemic factors, including obesity, diabetes mellitus, metabolic syndrome, and hormonal changes." (PMID 41300847, 2025). "Impaired leptin signaling is also a contributing factor to the development of obesity and, in turn, type 2 diabetes." (PMID 40289994, 2025). "These monogenic non-syndromic obesity disorders are mainly driven by molecular alterations in hypothalamic pathways involved in appetite regulation and weight regulation through the leptin-melanocortin pathway." (PMID 40822950, 2025). "Among children with obesity, clinical studies have shown that SDB is associated with increased pro-inflammatory cytokines, elevated leptin levels, reduced adiponectin, and higher prevalence of EDS." (PMID 40893196, 2025). "Leptin (LEP), produced by adipocytes, regulates obesity in animals by interacting with LEPR in hypothalamic neurons." (PMID 40735833, 2025). "Obesity-induced leptin and IGF-1 can activate NF-kB transcription, leading to an increase in cytokines." (PMID 40722609, 2025). "These saturated fatty acids alter the hypothalamic control of energy homeostasis by inducing hypothalamic inflammation and insulin and leptin resistance, thereby promoting obesity." (PMID 40690443, 2025). "Increased leptin levels and strong correlations between leptin, obesity, and HOMA-IR have been observed in studies including both patients with CCAH and NCCAH." (PMID 40529825, 2025). "Knockout of leptin signaling (or impaired receptor function secondary to obesity) in rodents induces depression-like behavior, while central or peripheral leptin administration has antidepressant effects." (PMID 40991698, 2025). "The results demonstrated that only male SstKO-MSD offspring developed obesity accompanied by severe insulin and leptin resistance after HFD challenge." (PMID 40066865, 2025). "Recent meta-analyses demonstrate that LEP and ADIPOQ promoter methylation strongly associate with obesity and weight-loss response." (PMID 41302083, 2025).
Obesity (continued). "The results of logistic regression analysis showed that obesity alone and type 2 diabetes with obesity were significantly associated with serum levels of TNF-α, IL-6, leptin, adiponectin, resistin, and ALR after adjusting for sex or age." (PMID 40095937, 2025). "Estradiol and leptin are considered key molecules in the pathophysiological mechanisms of obesity and TD." (PMID 40489567, 2025). "This review examines the functions of leptin and adiponectin, two key adipocytokines central to obesity, and evaluates the impact of yoga on these hormones." (PMID 39897330, 2025). "A study reports that GLP-1RAs partially reversed obesity-induced hypothalamic leptin resistance through microbiota-driven inosine." (PMID 41016636, 2025). "Overexpression of SOCS3 has been observed in microglia from obesity models, which can serve as a marker of leptin resistance." (PMID 41516046, 2025). "This pattern of expression of polygenic obesity genes is strikingly different from the one found in monogenic obesity where most of the gene (with the exception of LEP expressed in adipocytes) are expressed predominantly in the hypothalamus." (PMID 39237720, 2025). "Mice fed a high-fat diet (HFD), which had limited expression of PTP1B in the hypothalamic region, showed resistance to obesity and enhanced sensitivity to insulin/leptin." (PMID 40356976, 2025). "Obesity - induced adipokine disorders (such as increased leptin) upregulate hepatic hepcidin through the JAK2/STAT3 signaling pathway, inhibiting FPN-mediated iron efflux and leading to the accumulation of free Fe2+ in the liver." (PMID 40689204, 2025). "Leptin, a hormone secreted primarily by white adipose tissue, exerts neuroprotective effects in AD through multiple mechanisms that are disrupted in obesity-induced leptin resistance." (PMID 41155642, 2025). "Experimental studies have demonstrated that CNS-specific disruption of myeloid differentiation primary response 88 (MyD88), a critical adaptor for TLR-mediated NF-κB activation, protects mice from leptin resistance and diet-induced obesity." (PMID 41463063, 2025). "Previous research has consistently shown that individuals affected by both obesity and psoriasis exhibit significantly increased circulating leptin levels, alongside a marked reduction in adiponectin, when compared to healthy individuals." (PMID 41226468, 2025). "In most cases of common obesity, circulating leptin levels are elevated, yet its anorexigenic and weight-reducing effects are blunted—a phenomenon known as leptin resistance." (PMID 41251447, 2025). "Mechanistic studies implicate mitochondrial dysfunction and endoplasmic reticulum (ER) stress as key contributors, exemplified by POMC-specific Mitofusin 2 (Mfn2) deletion, which induces ER stress, leptin resistance, and obesity." (PMID 41409607, 2025). "The serum exosomes of Elafin-overexpressing HFD-treated mice showed an increase in miR-181b-5p and miR-219-5p, which can induce the expression of appetite reducing leptin in mouse mesenteric fat, thereby reducing obesity, hyperglycemia, and hepatic steatosis." (PMID 40129979, 2025). "This is further aggravated by imbalances in adipokines, such as adiponectin and leptin particularly in obesity." (PMID 40421243, 2025). "The present study aims to evaluate the inhibitory effects of Rha on leptin-induced VM in TNBC cells and to explore its potential as a novel therapeutic candidate for obesity-associated TNBC." (PMID 41463012, 2025). "In the context of leptin resistance—frequently observed in obesity and metabolic syndrome—leptin’s normal vasodilatory effects are blunted, while its mitogen-activated protein kinase (MAPK)-mediated vasoconstrictive and pro-inflammatory actions are preserved." (PMID 41470134, 2025). "The altered dynamics of leptin and insulin in obesity underscore the distinct roles of vWAT and sWAT in metabolic health." (PMID 41373779, 2025).
Obesity (continued). "Despite a positive correlation with obesity markers, leptin levels were significantly lower in newly diagnosed youth-onset T2DM compared to NGT and had a negative correlation with insulin resistance." (PMID 40630340, 2025). "Its link to cardiovascular disease is mainly through obesity driven by leptin resistance, but also through promoting inflammation, oxidative stress, and endothelial dysfunction." (PMID 39822062, 2025). "Leptin, an important adipokine, acts on molecular pathways such as PI3K/AKT and mTOR is encoded by the obesity gene and is involved in the process of regulating food intake." (PMID 40717997, 2025). "Both conditions result from primary cilia dysfunction, disrupting pathways such as leptin and insulin signaling, which leads to obesity and insulin resistance." (PMID 41312179, 2025). "Among them, recent advances in the comprehension of eating and energy regulation showed that around 60 genes involved in the hypothalamic leptin/melanocortin pathway contribute to the development of rare monogenic or syndromic forms of obesity." (PMID 40822950, 2025). "Acetate activates free fatty acid receptor two to stimulate leptin secretion in adipocytes, thereby regulating appetite and improving obesity." (PMID 40740992, 2025). "Elevated leptin and reduced adiponectin further raise blood pressure, contributing to obesity-related hypertension." (PMID 41155389, 2025). "This suggests that leptin contributes to the inflammatory milieu in obesity by upregulating CCL2, which in turn facilitates macrophage infiltration into WAT." (PMID 40518865, 2025). "Obesity, altered circulating concentrations of the adipose tissue‐derived hormones adiponectin and leptin, and hypertriglyceridaemia are additional features of EMS." (PMID 38984777, 2025). "The phenomenon of central leptin resistance is a key factor in the progression of obesity, and it extends its influence to peripheral tissues, including the liver, pancreas, platelets, vasculature, and myocardium." (PMID 40283443, 2025). "High leptin levels are directly correlated with obesity and subsequent development of metabolic disease consequences, including insulin resistance, type 2 diabetes, and cardiovascular disease." (PMID 40998755, 2025). "LPS is thought to initiate SOCS3 expression, disrupting leptin and insulin signaling in the brain and further paralleling obesity-related mechanisms." (PMID 41515969, 2025). "Most obesity-related compounds in the blood are also in saliva, i.e., insulin, leptin, α-amylase, tumor necrosis factor α/interleukin 6, C-reactive protein, and adiponectin." (PMID 40565251, 2025). "Key factors in obesity-induced inflammation include several adipokines (e.g., leptin, resistin, adiponectin), with their serum levels and corresponding receptor expression in adipose tissue serving as indicators of the obesity–psoriasis connection." (PMID 40893809, 2025). "Adipose tissue-derived hormones such as leptin, adiponectin, and resistin exert opposing effects on vascular homeostasis, influencing inflammation and oxidative stress in obesity and metabolic syndrome." (PMID 41155389, 2025). "Individuals with class II/III obesity exhibited higher leptin levels and lower 17α-OHPreg levels than healthy controls." (PMID 41140715, 2025). "Recent studies show that children with obesity are prone to have higher circulating leptin, which drops with decreasing BMI." (PMID 40282897, 2025). "Understanding the molecular crosstalk between leptin and GPCRs provides valuable insights for expanding leptin’s therapeutic potential and developing effective anti-obesity treatments." (PMID 41016636, 2025). "Paradoxically, the neuron-specific JNK3 isoform appears protective, with germline ablation exacerbating obesity through impaired leptin responsiveness." (PMID 40699756, 2025). "Leptin was higher and adiponectin was lower in groups with obesity and/or metabolically unhealthy status." (PMID 40362681, 2025).
Obesity (continued). "Targeting ER stress presents a promising therapeutic strategy to improve leptin sensitivity, boost energy expenditure, and ultimately address obesity." (PMID 41018420, 2025). "In addition to the role of the hypothalamic leptin-melanocortin pathway, several studies using genome-wide association study data have shown associations between gene variants, associated with energy metabolism and adipocyte biology, with body mass index (BMI) and obesity." (PMID 39929239, 2025). "Justification for interest in leptin was a demonstration that humans who are genetically unable to produce leptin experience intense hunger and display a high level of obesity, manifestations that can be abolished with leptin administration." (PMID 40077697, 2025). "On the other hand, chronically elevated levels of leptin in obesity induce resistance to the effects of the molecule and have been linked to impaired executive functions in older adults." (PMID 41403901, 2025). "Clinical and metabolic parameters, including insulin, HOMA-IR, leptin, and adiponectin levels, were measured to better describe the obesity profiles of the participants in this study." (PMID 40429924, 2025). "Obesity is frequently defined by leptin resistance, expressed as high leptin levels that fail to exert their physiological actions." (PMID 41375608, 2025). "Despite this, however, in obesity leptin resistance occurs with leptin failing to regulate these processes, resulting in overeating and weight gain." (PMID 40013194, 2025). "Collectively, it has been demonstrated that leptin-resistant mice, which develop obesity and a diabetic phenotype, exhibit elevated tau phosphorylation." (PMID 41516046, 2025). "The interplay of leptin resistance, inflammation, and disrupted signaling underscores the complex relationship between obesity, metabolic health, and thyroid function." (PMID 39857741, 2025). "Hormonal imbalances in obesity, such as short-term leptin activation and long-term suppression of NK cell function, further modulate their activity." (PMID 40999903, 2025). "Abnormalities in adipokine production (e.g., a decrease in adiponectin and an increase in leptin or pro-inflammatory cytokines) contribute to the development and progression of obesity, insulin resistance, type 2 diabetes, and cardiovascular complications." (PMID 40426925, 2025). "In obesity, adipose tissue generates large amounts of pro‐inflammatory mediators, including leptin, resistin, retinol‐binding protein 4 (RBP4), lipocalin 2, and cytokines such as IL‐6, IL‐1β, and TNF‐α." (PMID 40673471, 2025). "Obesity is also characterized by elevated levels of IR-inducing adipokines such as leptin, visfatin, and resistin." (PMID 41463398, 2025). "Transcriptomic analysis of the hippocampus showed disruption of pathways linked to obesity and cognitive decline in the MONW group, which were attenuated by leptin intake." (PMID 40944384, 2025). "As the pathogenesis of diabetes and obesity are interconnected, and leptin resistance also plays a role in pathological processes observed in diabetes, these findings are reasonable." (PMID 40725425, 2025). "Recent meta-analysis of current clinical studies in obesity demonstrates that GLP-1RA attenuates weight loss and decreases leptin serum levels." (PMID 41516046, 2025). "Together, these studies highlight the multiple mechanisms by which obesity (via elevated leptin, aberrant cytokine expression, and reduced adiponectin levels) impacts normal ovarian function." (PMID 40755647, 2025). "This is in agreement with our findings, where both rutin and nano-rutin (50 mg/kg) significantly reduced leptin levels in a preventive obesity model." (PMID 41007669, 2025). "We apply a state-space estimation framework using Bayesian filtering to infer continuous, long-term pro-satiety states from plasma leptin concentrations collected from premenopausal women with obesity." (PMID 41036146, 2025).
Obesity (continued). "Understanding the complex interaction between leptin, ghrelin, and their receptors in the hypothalamus is essential for uncovering the mechanisms that contribute to obesity and for developing specific therapeutic interventions." (PMID 40087612, 2025). "Ob/Ob mice show hyperphagia, obesity, insulin resistance and a low resting metabolic rate and administration of leptin to reverses these changes." (PMID 40635334, 2025). "Obesity causes dysfunctional PVAT that leads to decreased adiponectin levels and increased leptin and IL-6 levels and contributes to atherosclerosis progression." (PMID 40137085, 2025). "Accordingly, our data indicated an increase in serum leptin levels in HFD-fed rats that confirmed obesity in these groups." (PMID 41256259, 2025). "Conversely, mutations in a single gene regulating body weight mainly through the leptin-melanocortin pathway and involving less than 1% of children in tertiary pediatric clinics reflect non-syndromic monogenic obesity." (PMID 40370785, 2025). "The study investigates leptin, a hormone elevated in obesity, and finds that hyperleptinemia is common in TAD patients, suggesting its role in disease pathogenesis." (PMID 40667784, 2025). "Low ADP concentrations and an altered ratio between leptin and ADP are associated with obesity, altered insulin signaling, and an inflammatory state in obese patients." (PMID 40137085, 2025). "Women with obesity also showed markedly elevated mean serum leptin levels (55.1 ± 34.8 ng/mL; p < 0.001), as did those with abdominal obesity (45.2 ± 30.3 ng/mL; p < 0.001)." (PMID 41439942, 2025). "A randomized crossover trial in adults with overweight/obesity found that late eating increased hunger, reduced 24 h leptin levels, and elevated the ghrelin–leptin ratio, suggesting a stronger drive for food intake." (PMID 39997062, 2025). "In contrast, leptin, whose main function is to regulate appetite and energy balance, is elevated in individuals with obesity, reflecting a state of leptin resistance." (PMID 40289929, 2025). "Hyperleptinemia is present in obesity and T2DM, reflecting a state of leptin resistance associated with atherogenic processes, endothelial dysfunction, low-grade chronic inflammation, and vascular dysfunction." (PMID 41346429, 2025). "In another Danish study involving children aged 6–18 years with normal weight or overweight/obesity, those with overweight/obesity exhibited had higher leptin, lower adiponectin, and elevated L/A ratios compared to their normal-weight peers." (PMID 39857920, 2025). "Leptin (LEP), also known as an anti-obesity factor, is mainly encoded by obesity genes and secreted by white fat cells." (PMID 39997696, 2025). "Despite the expensive nature of the anti‐obesity treatments such as orlistat, statins, and leptin, obesity still remains at pandemic levels." (PMID 40255555, 2025). "A comparative analysis of the relationships between metabolic health/obesity and leptin and adiponectin was conducted using the same assessments." (PMID 40362681, 2025). "Taken together, these studies suggest that obesity, via elevated circulating leptin, induces a state of hypothalamic leptin resistance, with indirect effects on GnRH secretion, leading to ovulatory dysfunction and infertility." (PMID 40755647, 2025). "What’s more, to some extent, the HEH group was superior in improving obesity, liver function, and lipid metabolism, as well as regulating Leptin and LPS levels compared to the MEH group." (PMID 40735442, 2025). "Leptin and adiponectin levels, however, aligned with previously expected patterns for metabolic health and obesity in diverse populations." (PMID 40362681, 2025). "Leptin resistance and decreased adiponectin levels, commonly observed in individuals with obesity, impair neuromuscular control of the upper airway, thereby contributing to the pathogenesis of OSA." (PMID 41150735, 2025).